PRKAA1 (protein kinase AMP-activated catalytic subunit alpha 1)
Diseases named in the same sentence as PRKAA1 in open-access papers (continued):
Sharing a sentence is not in itself a finding about the gene and the disease.
chronic heart failure (1 paper, 2023). "Expression levels of PRKAA1, PRKACA, and PAK1 were increased in post-infarction chronic heart failure rats." (PMID 37405054, 2023). "The activities of PRKAA1, PRKACA, and PAK1 were significantly enhanced in post-infarction chronic heart failure." (PMID 37405054, 2023). "PRKAA1, PRKACA, and PAK1 might serve as potential therapeutic targets for post-infarction chronic heart failure." (PMID 37405054, 2023).
chronic myelomonocytic leukemia (1 paper, 2017). A myelodysplastic/myeloproliferative neoplasm which is characterized by persistent monocytosis, absence of a Philadelphia chromosome and BCR/ABL fusion gene, fewer than 20 percent blasts in the bone marrow and blood, myelodysplasia, and absence of PDGFRA or PDGFRB rearrangement. "PRKAA1 (5′-AMP-activated protein kinase catalytic subunit alpha-1) mediates autophagy during differentiation of human monocytesis and can potentially serve as a therapeutic target in chronic myelomonocytic leukemia." (PMID 28592245, 2017).
hyperlipidemia (1 paper, 2022). "Conversely, selective deletion of the protein kinase AMP-activated catalytic subunit α1 (Prkaa1) gene that encodes for AMPK-α1 in endothelial cells resulted in reduced endothelial cell proliferation as well as enhanced atherosclerotic formation in mice with hyperlipidemia." (PMID 35055468, 2022).
influenza (1 paper, 2025). An acute viral infection of the respiratory tract, occurring in isolated cases, in epidemics, or in pandemics; it is caused by serologically different strains of viruses (influenzaviruses) designated A, B, and C, has a 3-day incubation period, and usually lasts for 3 to 10 days. "Considering the expression of Prkaa1 and Prkaa2 in control Treg cells of influenza-infected lungs, as well as the compromised tissue-protective function of AMPKα1/α2–deficient Treg cells during viral pneumonia, these data suggest that AMPKα1 and AMPKα2 share redundant functions in this context." (PMID 40100289, 2025). "We confirmed that AMPKα1/α2 are dispensable for Treg cell–mediated immune self tolerance but found that Prkaa1/2fl/flFoxp3YFP–Cre mice grew smaller tumors and experienced greater mortality and hypoxemia during influenza, with evidence of greater intratumoral and lung immune activation." (PMID 40100289, 2025).
lentivirus infection (1 paper, 2018). Virus diseases caused by the Lentivirus genus. "As a result, the expression of genes encoding AMPKα1 and AMPKα2 (Prkaa1 and Prkaa2, respectively) and total AMPKα in iWAT-SVF cells were significantly reduced and the activation of AMPK signaling by A-769662 was successfully blocked after Cre lentivirus infection." (PMID 29515462, 2018).
lymph-node metastases (1 paper, 2023). "Instead, only a decreased expression of SQSTM1 (p = 0.006), TFEB (p = 0.011), and PRKAA1 (p = 0.001) could be observed in patients with lymph-node metastases (n = 17)." (PMID 36835048, 2023).
metabolic syndrome (1 paper, 2020). A cluster of metabolic risk factors for CARDIOVASCULAR DISEASES and TYPE 2 DIABETES MELLITUS. "We examined whether Prkaa1 deficiency-mediated decreased leukocyte recruitment affects diet-induced metabolic syndrome." (PMID 33511118, 2020).
ovarian tumor (1 paper, 2024). "Activation of PRKAA1 inhibits glycolysis, promotes mitochondrial function, induces cell cycle arrest, and reduces cell proliferation in ovarian tumor cells." (PMID 39342345, 2024).
postherpetic neuralgia (1 paper, 2023). "This study aimed to explore the relationship between genetic polymorphisms of AMPK gene (Rs13361707, rs3792822, and rs10074991) in PRKAA1 and postherpetic neuralgia (PHN) in Chinese individuals." (PMID 36818655, 2023).
pregnancy (1 paper, 2025). The status during which female mammals carry their developing young (EMBRYOS or FETUSES) in utero before birth, beginning from FERTILIZATION to BIRTH. "Nevertheless, indirect evidence suggests that the putatively adaptive PRKAA1 variant may support perinatal lung development in highland Andeans, which can be impeded by maternal hypoxia or the hypertensive disorder of pregnancy, pre-eclampsia, at altitude and also by AMPK deficiency in mice." (PMID 40836810, 2025).
tendinopathy (1 paper, 2025). "Here we have demonstrated that AMPK signaling is dysregulated in human tendinopathy patients and Prkaa1 is necessary to maintain homeostasis in adult mouse Achilles tendon." (PMID 39975248, 2025).
thyroid cancer (1 paper, 2023). "Five hundred and sixty-seven miRNAs associated with nine autophagy proteins (ULK1, ATG16L1, MAP1LC3B, PRKAA1, ATG12, ATG 14, ATG5, mTOR and BECN1) were identified, of which sixty-two are accompanied by thyroid cancer, and only miR-125b is associated with the autophagy modulation in this pathology." (PMID 36980957, 2023).
viral pneumonia (1 paper, 2025). Inflammation of the lung parenchyma that is caused by a viral infection. "We found that AMPKα1/α2–sufficient Treg cells express both Prkaa1 and Prkaa2 in lymph nodes and the lung during viral pneumonia and that steady-state splenic AMPKα1/α2–deficient Treg cells have downregulated expression of genes activated during influenza A virus infection." (PMID 40100289, 2025).
tumor (84 papers, 2012 to 2025). "Cancer cell-derived GM-CSF also induces transcription of the genes encoding AMP-activated protein kinase alpha (AMPKα) and Prkaa1 in tumor-MDSCs, regulating the differentiation of M-MDSCs to TAMs and exerting immunosuppressive effects." (PMID 38609997, 2024). "Interestingly, the levels of autophagy-related genes were positively associated with group 1 tumor tissues (PRKAA1 up-regulated patients), but negatively associated with group 2 tumor tissues (PRKAA1 down-regulated patients)." (PMID 33172060, 2020). "This is supported by the positive correlation between the expression levels of AR, CDH2, PRKAA1 and tumor purity." (PMID 39342345, 2024). "The obtained expression patterns of PRKAA1 and PRKAA2 mRNA, along with the proteins that they encode, indicate the induction of hypoxia in the tumor microenvironment." (PMID 39001398, 2024). "have demonstrated the tumor suppressor role of AMPK-α1 by utilizing T-cell-specific knock-outs of Pten and Prkaa1 gene encoding AMPK-α1." (PMID 36875093, 2023). "PRKAA1 expression was moderately positive in normal renal tissues (moderate in renal tubular cells) and weakly positive in tumor tissues according to CAB005050 staining." (PMID 37056387, 2023). "The knockdown of circC6orf132 facilitated the miR-873-5p expression but downregulated the protein level of PRKAA1 after qRT-PCR and Western blotting detection in tumor tissues." (PMID 34659329, 2021). "PRKAA1 encodes for the adenosine monophosphate activated protein kinase (AMPK), which regulates tumor growth and proliferation by regulating energy metabolism." (PMID 34305997, 2021). "Tumor growth and glycolysis were also retarded by knockdown of circC6orf132 in vivo through the mediation of miR-873-5p and PRKAA1." (PMID 34659329, 2021). "Arguing against this in the case of PRKAA1, however, is analysis of simultaneous genetic changes in known oncogenes and tumour suppressors that occur within the same cases of cancer." (PMID 33375416, 2020). "Five of forty-two tumor tissues showed significantly up-regulated expression of AMPKαl (PRKAA1) (Group 1) (red bars), whereas another six tumor tissues showed significantly down-regulated expression of AMPKαl (PRKAA1) (Group 2) (green bars)." (PMID 33172060, 2020). "PDCD4, NKX2-1 and PRKAA1 (AMPKA1) are well known tumor supressor genes, and our result suggests that DTL downregulates these genes." (PMID 28336923, 2017). "Nonetheless, the tumor data reinforce the possible involvement of cell cycle homeostasis and autophagy as PRKAA1 and PIK3C3 were the top 2 ranked genes." (PMID 28030792, 2017). "However, other studies showed that if the Prkaa1 gene was knocked out in mice after T-ALL had arisen the disease was ameliorated, showing that in that context AMPK-α1 could act as a tumour promoter." (PMID 37962491, 2023). "However, the PRKAA1 gene, encoding AMPK-α1, displayed exactly the opposite behaviour in that it was amplified in many cancers, which is what one might expect for a tumour promoter." (PMID 36383046, 2022). "We assessed the production of IFN-γ and TNF-α by tumor-infiltrating CD8+ T cells and found a significantly greater proportion of IFN-γ+CD8+ T cells in tumors of Prkaa1/2fl/flFoxp3YFP–Cre mice." (PMID 40100289, 2025). "Strikingly, all three kinases (i.e. PRKAA1, PRKAA2, and EEF2K) regulating cell metabolism were found to contribute to HGG cell viability, providing a novel tumor vulnerability." (PMID 31420543, 2019). "PRKAA1 (protein kinase AMP-activated α1 catalytic subunit), a subunit of AMPK, has been shown to be overexpressed in GC tissues and promote energy metabolism and tumor progression in GC." (PMID 39816354, 2024). "Similarly, RRM2B (nucleotide biosynthesis), PRKAA1 (AMPK signaling), and RICTOR (mTOR signaling) had widespread copy number gains exclusively in glycolytic cancers, apart from RRM2B, which had copy number gains in ~30% of evaluated PRAD patient tumor genes." (PMID 36831501, 2023).
tumor (continued). "Fourth, all the 10 articles included in our meta-analysis lacked information about PRKAA1 expression levels classified by gender or stage of the tumor; hence, we could not analyze these factors." (PMID 28978122, 2017).
cancer (69 papers, 2008 to 2026). A tumor composed of atypical neoplastic, often pleomorphic cells that invade other tissues. "While the PRKAA2 gene (encoding AMPK-α2) is subject to relatively frequent mis-sense mutations in human cancers, the PRKAA1 gene is rarely mutated but is instead often amplified, especially in lung adenocarcinomas." (PMID 37962491, 2023). "and (ii) why is it only the PRKAA1 gene (encoding the α1 isoform) that is amplified in some cancers?" (PMID 36383046, 2022). "Recent analyses of this database revealed that, while the PRKAA2 gene encoding AMPK-α2 is often mutated in human cancers, the PRKAA1 gene encoding AMPK-α1 (also, interestingly, the PRKAB2 gene encoding AMPK-β2) is often amplified instead." (PMID 33375416, 2020). "Initially, we enrolled all eligible studies focused on the relationships between PRKAA1 polymorphisms and overall cancer risks to conducted a comprehensive meta-analysis." (PMID 30340465, 2018). "The polymorphism rs13361707 is located in the first intron of PRKAA1 gene, which is a cellular energy sensor maintaining energy homeostasis, and contributes to cancer development by regulating mRNA translation and protein synthesis." (PMID 30253744, 2018). "Currently, several studies have demonstrated that PRKAA1 polymorphisms conduce to the development of cancer." (PMID 30340465, 2018). "In many cancer genome studies, including the Cancer Cell Line Encyclopedia68, the PRKAA1 and PRKAB2 genes (encoding α1 and β2) tend to be amplified together (P < 0.01), suggesting that there has been selection for amplification of both genes." (PMID 26934201, 2016). "In addition, GM-CSF derived from cancer cells induces the transcription of AMPKα1 encoding gene Prkaa1 in MDSCs in a STAT5-dependent manner." (PMID 33027968, 2020). "Thus, we performed a systematic review and meta-analysis of all enrolled eligible case-control studies to obtain a precise correlation between PRKAA1 polymorphism and cancer susceptibility." (PMID 30340465, 2018). "Herein, we managed the meta-analysis to assess whether PRKAA1 polymorphisms affect susceptibility of cancer." (PMID 30340465, 2018). "By contrast with STK11, mutations in PRKAA1 are infrequent (approximately 0.1% of all cancer cases) and around 80% of those that do occur are missense mutations that may not affect function (green symbols)." (PMID 26934201, 2016). "Specifically, the E6 oncoprotein induces PRKAA1 overexpression in cancer cells such as C-33A and U-2OS cells, whereas coexpression of E6 and E7 decreases PRKAA1 expression." (PMID 41596244, 2026). "By means of TWAS, we recovered seven genes (APOC1, APOE, BIN1, HMGB1, PRKAA1, SQSTM1, and UCP2) significantly associated to AD traits and some cancer models." (PMID 31608105, 2019). "In-silico analysis was performed to demonstrate the relationship of PRKAA1 expression correlated with cancer tissues and survival time." (PMID 30340465, 2018). "PRKAA1 is a gene e that encodes adenosine monophosphate-activated protein kinase (AMPK), a central metabolic switch involved in various diseases related to energy metabolism, particularly cancer." (PMID 37670284, 2023). "Our data have successfully elaborated that PRKAA1 rs13361707 polymorphism is not participant with increased risk of cancer, while the A allele of PRKAA1 rs10074991 revealed a significant decrease risk, especially in Asian population." (PMID 30340465, 2018). "For example, the PRKAA1 gene encodes catalytic α-subunit of 5′ AMP-activated protein kinase, which is involved in protecting tumors from energy deprivation and thus promoting cancer metastasis." (PMID 27821817, 2017). "Thus, amplification of the PRKAA1 gene appears to have been selected for in different cancers, suggesting that it is an oncogene." (PMID 26934201, 2016). "Indeed, AMPK inhibitors might be particularly useful in treating cancers where the PRKAA1 gene is amplified, which include at least 10% of all cases of human lung adenocarcinoma." (PMID 38203624, 2023).
cancer (continued). "However, little is known about the role of PRKAA1 in cancer development." (PMID 29769411, 2019). "However, cBioPortal reveals that, in the same cancer genome studies where STK11 is mutated or deleted, the PRKAA1 gene encoding α1 is often amplified, with the highest frequency (10–15%) also occurring in lung adenocarcinomas (note the preponderance of red bars)." (PMID 26934201, 2016). "Recent studies have highlighted the significance of PRKAA1 and PRKAA2 in tumorigenesis and cancer progression." (PMID 39001398, 2024). "Protein kinase AMP-activated catalytic subunit alpha 1 (AMPK) enhances the glycolytic activity of PFKFB3 by phosphorylating PFKFB3 at Ser461, and therefore, promoting the proliferation of cancer cells." (PMID 37253634, 2023). "Here, we report that AMP-activated protein kinase alpha 1 (AMPKα1, PRKAA1) is positively involved in autophagy induction and cancer progression by regulating TRAF6-BECN1 signaling axis." (PMID 33172060, 2020). "In BC, the low expression of SMARCA2 correlates with higher PRKAA1 and PKM2 expression indicative of its important role in the control of metabolic processes in this cancer type." (PMID 32073734, 2020). "These genes, such as PRKAA1, PLCE1 and MUC1, also play an important role in cancer progression and tumorigenesis." (PMID 27821817, 2017). "At present, there is no clear report that PRKAA1 is involved in hair follicle development, but it plays an important role in cell proliferation, such as cancer and muscle cells." (PMID 32549352, 2020). "MAGEA3 (MAGE family member A3)/MAGEA6 are frequently reactivated in cancer cells and bind to the TRIM28 E3 ligase, which ubiquitinates PRKAA1/AMPKα1 (protein kinase AMP-activated catalytic subunit alpha 1), promoting the degradation of AMPK and the inhibition of autophagy." (PMID 32887506, 2020). "PRKAA1, a subunit of the AMPK pathway, is critical to cellular activity and cancer development, and studies have demonstrated its role in cell differentiation, apoptosis, autophagy, and cancer progression as well as in clinical prognosis." (PMID 26485766, 2015). "In addition, we analyzed whether the expression of PRKAA1 affects the overall survival (OS) and disease free survival (RFS) of these four cancers." (PMID 30340465, 2018). "Interestingly, the low rather than high levels of CSNK1E, IGF2R, IRAK3, and PRKAA1 relate to poor cancer prognosis, suggesting that kinases often play a divergent role in different types of cancer." (PMID 26956052, 2016). "We observed the overexpression of isoforms of genes C3orf17, FRMD4A, FZD6, HNRNPA2B1, POSTN, PRKAA1, RRBP1 and VEGFA, and the under expression of TRIP12 isoform (ENST00000428959) in ACC patients who are not free of cancer, which is a surrogate for poor ACC outcomes." (PMID 33035235, 2020). "Analysis of these cancers has the advantage that cells of the haemopoietic lineage only express the α1 and not the α2 isoform of the AMPK catalytic subunit, so that to study the effect of lack of AMPK it is only necessary to knock out one gene (Prkaa1) rather than two." (PMID 33375416, 2020).
infection (16 papers, 2010 to 2024). The state of being infected such as from the introduction of a foreign agent such as serum, vaccine, antigenic substance or organism. "For PRKAA1 rs13361707, we found significant associations between PRKAA1 rs13361707 and decreased risk of GC in subjects with Types I and II infection, and the ORs were 0.46 (95% CI: 0.29–0.73) and 0.39 (95% CI: 0.20–0.78), respectively." (PMID 28220687, 2017). "For MUC1 rs4072037, similar significant associations between PRKAA1 rs13361707 and decreased risk of GC were found in subjects with both Types I and II infection." (PMID 28220687, 2017).
cardiovascular diseases (3 papers, 2020 to 2024). "A few groups have extensively studied the role of AMPKα1/PRKAA1 in regulating cardiovascular functions and the development of cardiovascular diseases." (PMID 33511118, 2020).
adenocarcinoma (1 paper, 2023). A common cancer characterized by the presence of malignant glandular cells. "Stratification analysis revealed that the effects of these SNPs in PTGER4 and PRKAA1 on GC susceptibility were dependent on smoking and were associated with a reduced risk of adenocarcinoma (p < 0.05)." (PMID 37670284, 2023). "Stratified analysis suggests a protective effect of PRKAA1 rs10074991 and rs13361707 on GC in non-smokers, and rs10074991 was also associated with GC adenocarcinoma." (PMID 37670284, 2023).
PRKAA1 also shares sentences with these, for which no sentence is quoted: non-small cell lung carcinoma (9 papers); colon carcinoma (8); heart failure (6); hepatocellular carcinoma (6); Hyperglycemia (5); osteoarthritis (5); ovarian carcinoma (5); Arthritis (4); glioblastoma (4); metabolic disorders (4); myocardial infarction (4); pulmonary hypertension (4); bacterial infection (3); cardia (3); colitis (3); Hypertension (3); pancreatic cancer (3); acute liver failure (2); acute lung injury (2); anaemia (2); cardiac ischemia (2); chondrosarcoma (2); Cognitive impairment (2); colorectal adenocarcinoma (2); emphysema (2); H. pylori (2); Hypercholesterolemia (2); Impaired glucose tolerance (2); iron deficiency (2); ischemia (2).
A further 92 diseases each share a sentence with PRKAA1 in 2 papers or fewer.